CAV1 (caveolin 1)
Diseases named in the same sentence as CAV1 in open-access papers (continued):
Sharing a sentence is not in itself a finding about the gene and the disease.
Ewing sarcoma (16 papers, 2011 to 2025). A small round cell tumor that lacks morphologic, immunohistochemical, and electron microscopic evidence of neuroectodermal differentiation. "Their in vitro trial demonstrated that the silencing of the metastasis-associated CAV1 gene, which expresses the CAV1 integral protein, was related to reduced endothelial cell migration in Ewing’s sarcoma." (PMID 35563562, 2022). "Many of the top ranked super-enhancer associated genes were genes of known relevance in Ewing sarcoma, including caveolin 1 (CAV1), NKX2.2, ID2 and CCND1." (PMID 26337082, 2015). "We then examined the individual gene tracks of two of the largest super-enhancers in Ewing sarcoma, which were associated with CAV1/2 and CCND1." (PMID 26337082, 2015). "The suppression of EWS/FLI1 also leads to a selective decrease in protein expression of the Ewing sarcoma super-enhancer-associated genes CAV1 and CCND1 versus a vinculin control." (PMID 26337082, 2015). "Later on, CAV1 with other 3 proteins was considered a differential diagnostic immunomarker for Ewing's sarcoma/PNET in a sample of 415 genetically confirmed cases." (PMID 21471610, 2011). "Dysregulation of CAV1 has been associated with the metastases in other cancer models and expression of CAV1 is necessary for maintenance of oncogenic transformation in patient-derived Ewing sarcoma cell lines." (PMID 24704979, 2012). "In contrast, Cav-1 restoration promoted resistance to chemotherapy-induced apoptosis in Ewing's sarcoma cells." (PMID 26431273, 2015). "Likewise, their in vitro findings were in line with in vivo outcomes after the implantation of three Ewing’s sarcoma cells with the CAV1 gene silencing profile and low expression of CAV1 transmembrane protein." (PMID 35563562, 2022). "The expression of the selected target genes in Ewing’s sarcoma (CAV1, NR0B1, IGFBP3 and TGFBR2), together with the expression of HIST1H4L, KCNN2, ECRG4 and LDOC1, was then validated in an independent series of PCa with and without ETS gene fusions, as well as in a series of ESFT and ARMS." (PMID 23185447, 2012). "Reexpression of CAV1 or E-cadherin in CAV1 knockdown Ewing's sarcoma cells rescued the oncogenic phenotype of the original Ewing's sarcoma cells, showing that the CAV1/Snail/E-cadherin pathway plays a central role in the expression of the oncogenic transformation functions of EWS/FLI-1." (PMID 21471610, 2011). "Consistently, loss of CAV1 expression inhibited the anchorage-independent growth of EWS cells and markedly reduced the growth of Ewing's sarcoma cell-derived tumors in nude mice xenografts, indicating that CAV1 promotes the malignant phenotype in Ewing's sarcoma carcinogenesis." (PMID 21471610, 2011). "For example, in Ewing sarcoma (ES) EphA2 promoted angiogenesis via ligand- (and caveolin-1)-dependent signaling, while en-hancing tumorigenicity, migration and invasion in vitro and in vivo, in an S897 depend-ent manner." (PMID 33572284, 2021). "In Ewing sarcoma (ES), cell surface markers such as CD99, Fli-1, and caveolin-1 are used in diagnostics, while glycosphingolipid ganglioside antigen G (D2) (GD2) can serve as a possible target for anti-GD2 monoclonal antibody therapy." (PMID 40134582, 2025). "The GGAA-microsatellite of two critical upregulated EWS/FLI-targets in Ewing sarcoma (NR0B1 and CAV1) have been shown to be highly polymorphic in African and white European populations, with a predisposition for significantly larger GGAA-microsatellites in Africans, especially at the NR0B1 locus." (PMID 25093581, 2014).
Hepatic steatosis (16 papers, 2017 to 2025). Steatosis is a term used to denote lipid accumulation within hepatocytes. "Previous studies have shown that global Cav1 deficiency affects lipid metabolism and hepatic steatosis." (PMID 32029710, 2020). "To further address the potential molecular mechanisms underlying the hepatic CAV1 depletion-induced exacerbation of fatty liver disease, we examined the expression of genes regulating fatty acid homeostasis in FFA-treated hepatocytes." (PMID 28570612, 2017). "Furthermore, the deficiency of CAV1 in mouse models fed an HFD notably exacerbated hepatic steatosis, inflammation, and fibrosis." (PMID 39781461, 2025). "The second possible molecular mechanism underlying CAV1-regulated hepatic steatosis might lie in the inhibition of PPARα, which is essential in the modulation of lipid metabolism as it activates the mitochondrial and peroxisomal fatty acid β-oxidation pathways." (PMID 28570612, 2017). "Elucidation of the molecular mechanisms by which CAV1 loss mediates lipid accumulation in liver steatosis may have an important clinical impact, and hence, gene-therapy approaches to overexpress CAV1 might be of utility to ameliorate or even reverse NAFLD in humans." (PMID 28570612, 2017). "Mechanistically, Cav-1 overexpression alleviates autophagy inhibition by suppressing Akt/mTOR signaling, and then degrades lipid droplets and reduces liver steatosis." (PMID 41030451, 2025). "Dysfunctional CAV1 leads to hepatic steatosis and an altered mitochondrial metabolism and is associated with cholesterol-mediated mitochondrial dysfunction." (PMID 36674967, 2023). "This has been borne out in several studies, and we have proven that CAV1 overexpression by AAV2/8CAV1 treatment prevented LD feeding-induced hepatic steatosis and abnormal lipid metabolism by reducing SREBP1c expression via AMPK pathway activation." (PMID 36303150, 2022). "In contrast, the protective effect of CAV1 on alcoholic fatty liver was reported to lie in reducing oxidative stress." (PMID 34305621, 2021). "CAV1 knockout was reported to augment hepatic steatosis in the livers of high fat fed mice with NAFLD." (PMID 34305621, 2021). "While in the Asterholm study, opposite results were shown, i.e., that Cav1 knockout mice had reduced hepatic steatosis after 8 weeks HFD in response to 24 h fasting." (PMID 32029710, 2020). "Last, the expression of caveolin 1 (CAV1), a marker of lipid regulation and mitochondrial signaling which is known to have a protective role against hepatic steatosis and hepatocyte injury in NAFLD was tested." (PMID 32481590, 2020). "As illustrated by the analysis of Cav1, Fabp4, and Cd36 expressions and their relations with hepatic steatosis, the liver has a robust metabolic network that includes multiple regulators contributing its plasticity in coping with the challenge of MF diet." (PMID 29266667, 2018). "Whole-body caveolin 1 knockout (cav1−/−) reduced hepatic steatosis in high fat fed mice in response to 24 h of fasting, whereas liver-specific caveolin 1 knockout did not affect hepatic fat content." (PMID 29936596, 2018). "Next we fed WT and CAV1-KO mice with an HFD to assess the effect of HFD exposure on CAV1-regulated hepatic steatosis." (PMID 28570612, 2017). "To further evaluate and determine the role of CAV1 in the pathogenesis and development of hepatic steatosis, we performed experiments using CAV1-KO mice." (PMID 28570612, 2017). "In conclusion, this study provides a framework for understanding the protective potential of CAV1 against hepatic steatosis and hepatocyte injury in NAFLD, which is probably due to its functions in modulating the expression of lipid metabolism genes." (PMID 28570612, 2017). "In addition, our previous studies have shown that alcohol-induced fatty liver mice are more susceptible to APAP-induced liver injury, and that CAV1 seems to have a protective effect on APAP and alcohol consumption." (PMID 35886933, 2022).
Hepatic steatosis (continued). "To verify whether CAV1 prevents APAP-aggravated hepatic steatosis by suppressing Ang II/EGFR/ERK signaling and promoting autophagy, we applied two inhibitors to L02 cells." (PMID 35886933, 2022). "Interestingly, caveolin-1 overexpression protected and caveolin-1 knockout aggravated hepatic steatosis in HFD-fed mice by affecting lipogenesis, which indicates regulatory functions of caveolin-1 other than lipid transport in the liver." (PMID 33548031, 2021). "To date, the molecular mechanisms by which CAV1 mediates liver steatosis, especially in diet-induced fatty livers, remain unclear." (PMID 28570612, 2017). "We sought to obtain novel insights into the role of CAV1 in pathological hepatic steatosis." (PMID 28570612, 2017). "Collectively, these results suggested that CAV1 might play a role in the development of diet-induced fatty liver disease." (PMID 28570612, 2017). "Moreover, truncated OxPAPC down-regulated the expression of Cav1 (caveolin 1), which has been shown to increase hepatic lipid droplet size in NAFLD, and up-regulated Slc25a1, which has recently been associated with hepatic steatosis and glucose intolerance by dysregulation of hepatocyte metabolism." (PMID 35857497, 2022). "Moreover, a clinical study confirmed that serum CAV1 levels in heavy drinkers was negatively correlated with the degree of alcoholic liver injury, which makes the study of CAV1 more meaningful, especially for patients with alcoholic fatty liver who need acetaminophen to relieve fever and pain." (PMID 35886933, 2022). "Consistent with CAV1 repression in the livers of HFD-induced mice, the CAV1-KO mice exhibited more severe hepatic steatosis upon HFD intake." (PMID 28570612, 2017). "Similarly, when caveolin-1 (CAV1), a structural caveolae protein in the plasma membrane related to hepatic lipid translocation, is ablated in HFD mice, liver steatosis is reduced while hepatic gluconeogenesis is elevated." (PMID 35501558, 2022). "We report that hepatocyte-specific CAV1 does not affect liver steatosis and fibrosis in the MCD induced NAFLD model, but impacts severely on gene expression profiles, especially in diseased livers of males and females." (PMID 32029710, 2020). "This influenced hepatic steatosis, thus arguing for a non-hepatic CAV1 control of liver metabolic alterations." (PMID 32029710, 2020). "However, compared with the Flox mice, there was no significant increase in hepatic steatosis in the Cav-1-CKO mice." (PMID 37941054, 2023). "Hence, the lack of hepatocyte CAV1 is not a critical factor for the development of liver steatosis and fibrosis in the MCD model." (PMID 32029710, 2020). "In conclusion, our results demonstrate that hepatocyte-specific Cav1 knockout significantly altered gene profiles, did not affect liver steatosis and fibrosis in NAFLD and that gender had severe impact on gene expression patterns in healthy and diseased hepatocyte-specific Cav1 knockout mice." (PMID 32029710, 2020). "We thus directly tested whether CAV1 is required for protection against hepatic steatosis in vivo by examining mice that lacked CAV1." (PMID 28570612, 2017). "Additionally, we showed that mice lacking CAV1 developed more-severe hepatic steatosis when fed an HFD, demonstrating that CAV1 protects against the development of hepatic steatosis and hepatocyte injury that is involved in NAFLD." (PMID 28570612, 2017).
lung diseases (16 papers, 2012 to 2025). "Cav‐1 has been closely linked to lung diseases, including the development of lung mesenchymal fibrosis, where its expression is downregulated." (PMID 40778471, 2025). "Thus, searching for Cav–1 mutations and polymorphisms may be important in determining the roles of Cav–1 in the pathogenesis of lung disease." (PMID 35911737, 2022). "Caveolin‐1 (Cav‐1), encoded by CAV1, is a component of the caveolae in the cell membrane, which has been shown to be associated with many lung diseases, including PH." (PMID 40066229, 2025). "The important effects of Cav-1 on the lungs indicate that Cav-1 can be a potential target for the treatment of lung diseases." (PMID 39380904, 2024). "Particularly, the MAPK, NF-κB, TGFβ/Smad, and eNOS/NO signaling pathways have been involved in the regulatory effects of Cav-1 in lung diseases." (PMID 39380904, 2024). "The phosphorylation of Cav‐1 at Tyr14 can be regulated in posttranslational level to contribute to the pathogenesis of lung diseases." (PMID 32508059, 2020). "The first evidence for the involvement of caveolin-1 in lung disease was provided by a study of radiation-induced fibrosis in rat and mini-pig lungs." (PMID 29026006, 2017). "A linkage between the caveolin-1 signaling and cell adhesion molecules in the pathobiology of lung diseases was also reported." (PMID 29026006, 2017). "Some studies demonstrated that in cardiovascular and pulmonary diseases, Cav-1 could inhibit eNOS activity, thereby affecting normal angiogenesis and barrier function." (PMID 37229256, 2023). "Altogether, these data suggest a strong antimitogenic role for caveolin-1 in airway mesenchymal cells, suggesting that abnormal caveolin-1 expression might be involved in fibroproliferative lung diseases." (PMID 37759535, 2023). "Up and down regulation of Cav–1 can contribute to lung disease through several mechanisms." (PMID 35911737, 2022). "The widespread presence of Cav–1 increases controllability and may influence the pathophysiology in severe lung disease states." (PMID 35911737, 2022). "In most of the lung diseases, the expression of Cav‐1 is lower compared to normal conditions." (PMID 32508059, 2020). "Thus, the widespread presence of caveolae raises the controllability of themselves and Cav‐1 in lung disease states and can in turn influence the pathophysiology." (PMID 32508059, 2020). "CAV1 expression is reduced in fLfs in fibrotic lung disease." (PMID 32841217, 2020). "In addition to caveolin-1, possible importance of the less-studied endothelial caveolin-2 in pulmonary diseases will be also discussed." (PMID 26605130, 2012). "In addition to overwhelming evidence for the role of endothelial caveolin-1, more recent studies also suggest that endothelial caveolin-2 could possibly play a role in pulmonary disease." (PMID 26605130, 2012). "Although Cav-1 plays an important role in lung diseases, regulatory mechanisms that control Cav-1 gene/protein expression by growth factors have not been well defined." (PMID 25658089, 2015).
scleroderma (16 papers, 2010 to 2025). Scleroderma is a rare autoimmune connective tissue disorder characterized by abnormal hardening of the skin and, sometimes, other organs. "The lowered expression of Cav‐1 in the skin tissue of SSc patients has prompted researchers to adopt Cav‐1‐deficient mice as an innovative preclinical model for investigating scleroderma." (PMID 40778471, 2025). "In scleroderma patients, the decreased levels of Cav1 serve as a risk factor for the differentiation of monocytes to spindle-shaped fibrocytes." (PMID 33015095, 2020). "Monocytes from systemic sclerosis (SSc, scleroderma) patients and healthy African Americans (AA) are deficient in the regulatory protein caveolin-1 leading to enhanced migration toward chemokines and fibrogenic differentiation." (PMID 28420992, 2017). "A study indicates that enriched genes including MPO (myeloperoxidase), RXFP1, CXCL11, CTNND2, BMPR2, TLR3, CCR2, and CAV1 are altered expressed in scleroderma." (PMID 38137330, 2023). "Integrin subunit alpha V (ITGAV) and caveolin 1 (CAV1) interactions were specific to scleroderma fibroblasts." (PMID 37443817, 2023). "Predictably, hyperactivation of several members of the MAPK family of signaling molecules (ERK, JNK, p38) was also observed in CAV-1-reduced monocytes from scleroderma patients." (PMID 30644419, 2019). "ITGAV and CAV1 interactions were only among the top interactions in scleroderma fibroblasts." (PMID 37443817, 2023). "On the other hand, an increase in Cav-1 expression decreases the α-SMA expression in scleroderma fibroblasts, but not in normal fibroblasts." (PMID 31044089, 2019). "Another study showed that overexpression of Cav-1 inhibits production of collagen, tenascin, and SMA-α, whereas Cav-1 silencing has the opposite effect, and that CSD peptide alone has the same effects, both in normal and scleroderma patient-derived fibroblasts." (PMID 29250058, 2017). "In considering the molecular mechanism underlying the accumulation of CCR5 in scleroderma monocytes and its reversal by CSD, it is interesting to note that CCR5 is a G protein-coupled receptor and that caveolin-1 is known to bind to and modulate the function of G proteins." (PMID 24966836, 2014). "This is the first paper, in our knowledge evaluating the function of Cav-1 on the VEGF signaling in SSc, and particularly on MSC/pericyte lineage, showing that these pathways may strongly influence fibrotic process during scleroderma." (PMID 25237397, 2014).
fibrosis (15 papers, 2012 to 2023). the formation of excess fibrous connective tissue in an organ or tissue in a reparative or reactive process. "The malfunction of this caveolin-1 signal forwarding could also be associated with the pathogenesis of forced tissue fibrosis." (PMID 37894778, 2023). "Caveolin-1 has been shown to inhibit fibroblast autophagy by regulating Sequestosome 1, which decreases intestinal fibrosis in CD31." (PMID 37550393, 2023). "In our study, we noticed that the expression of CAV-1 was downregulated when we compared F1/F2 stages of fibrosis with healthy controls and in F3/F4 stages of fibrosis compared with healthy controls." (PMID 36556936, 2022). "Both airsacculitis score and fibrosis score were negatively correlated with the protein expression level of Cav-1 (r = −0.506, p < 0.01; r = −0.676, p < 0.01)." (PMID 27937011, 2017). "Using a DSS fibrosis model and in vitro studies with primary intestinal fibroblasts, their work shows that Caveolin-1 (CAV1) increases the expression of SQSTM1/p62 and inhibits autophagy, thus preventing fibroblast transdifferentiation and avoiding the accumulation of α-SMA and ECM." (PMID 37397491, 2023). "Therefore, it is speculated that CAV1 may affect intestinal fibrosis in CD by alleviating ferroptosis, but further studies are still needed to validate it." (PMID 37550393, 2023). "Furthermore, studies using cav-1 knockout mice and cav-1 deficient cells have shown that the elimination of cav-1 can protect against fibrosis both in vivo and in vitro, while having no adverse effects on blood pressure and renal function." (PMID 30995923, 2019). "Therefore, the inhibition of TGF-β production by reduced inflammasome activity might be involved in protective effect of Cav-1 gene transfer from bleomycin-induced fibrosis in this study." (PMID 31873099, 2019). "We observed that Cav-1 was highly expressed in alveolar epithelial type I cells in the normal lung, whereas expression of Cav-1 was greatly reduced in lungs from patients with IPF and bleomycin-induced fibrosis mouse model." (PMID 31873099, 2019).